TEN1 (TEN1 subunit of CST complex)
Description:
Component of the CST complex proposed to act as a specialized replication factor promoting DNA replication under conditions of replication stress or natural replication barriers such as the telomere duplex. The CST complex binds single-stranded DNA with high affinity in a sequence-independent manner, while isolated subunits bind DNA with low affinity by themselves. Initially the CST complex has been proposed to protect telomeres from DNA degradation. However, the CST complex has been shown to be involved in several aspects of telomere replication. The CST complex inhibits telomerase and is involved in telomere length homeostasis; it is proposed to bind to newly telomerase-synthesized 3' overhangs and to terminate telomerase action implicating the association with the ACD:POT1 complex thus interfering with its telomerase stimulation activity. The CST complex is also proposed to be involved in fill-in synthesis of the telomeric C-strand probably implicating recruitment and activation of DNA polymerase alpha. The CST complex facilitates recovery from many forms of exogenous DNA damage; seems to be involved in the re-initiation of DNA replication at repaired forks and/or dormant origins.
Synonyms: C17orf106; FLJ39785
Tractability: Small molecule: a structure with a bound ligand is known.
Gene: Protein-coding gene on chromosome 17 (75,979,235 to 76,000,587, forward strand). Ensembl gene ENSG00000257949.
Subcellular location: Nucleus; Chromosome, telomere
Subcellular location (Human Protein Atlas): Nucleoplasm
Pathways (Reactome):
Cell Cycle: Polymerase switching on the C-strand of the telomere; Telomere C-strand synthesis initiation
Gene Ontology:
Molecular function: protein binding; telomeric DNA binding; single-stranded DNA binding
Biological process: negative regulation of telomere maintenance via telomerase; telomere capping
Cellular component: chromosome, telomeric region; CST complex; nucleoplasm; nucleus
Genetic constraint (gnomAD): Loss-of-function variants: 11 observed, 14.8 expected, observed/expected ratio (o/e) 0.74, 90% interval 0.47 to 1.23. The upper end of that interval is the gene's LOEUF score, 1.23, which puts it in group 5 of 6, group 1 being the genes least tolerant of losing a copy. Missense variants: 149 observed, 165.08 expected, observed/expected ratio (o/e) 0.9, 90% interval 0.79 to 1.03. Synonymous variants: 65 observed, 68.35 expected, observed/expected ratio (o/e) 0.95, 90% interval 0.78 to 1.17.
Homologues: Orthologues: chimpanzee TEN1 (100% identical), macaque TEN1 (96% identical), pig TEN1 (80% identical), dog TEN1 (80% identical), guinea pig TEN1 (76% identical), rabbit TEN1 (76% identical), rat Ten1 (67% identical), mouse Ten1 (62% identical), tropical clawed frog ten1 (50% identical), zebrafish ten1 (41% identical).
Diseases named in the same sentence as TEN1 in open-access papers:
TEN1 is named in the same sentence as 20 diseases in open-access papers, as found by Europe PMC text mining. Sharing a sentence is not in itself a finding about the gene and the disease. The quoted sentences say what the papers report.
melanoma (2 papers, 2025). A malignant, usually aggressive tumor composed of atypical, neoplastic melanocytes.
teratospermia (2 papers, 2015 to 2018). "In the genetic study of teratospermia in the TEN1 mouse strain, at least three interacting loci, Shm3 on chromosome 1, Shm4 on X chromosome, and Shm5 on chromosome 6, have been identified." (PMID 30171338, 2018). "In this study, we analyzed if the teratozoospermia of the TEN1 strain is heritable, and then predicted the number of loci regulating the sperm‐head abnormal phenotype." (PMID 25559406, 2015).
Coats plus syndrome (1 paper, 2021). "Mutations in the telomere maintenance complex (the CST complex; CTC1, STN1, and TEN1) lead to cerebroretinal microangiopathy (Coats plus syndrome) with a failure of multiple organs." (PMID 34139671, 2021).
dyskeratosis congenita (1 paper, 2014). Dyskeratosis congenita (DC) is a rare ectodermal dysplasia that often presents with the classic triad of nail dysplasia, skin pigmentary changes, and oral leukoplakia associated with a high risk of bone marrow failure (BMF) and cancer. "Also, mutations in human CTC1, the ortholog of CDC13, are found in a number of diseases associated with telomere defects (Coats plus, dyskeratosis congenita and CRMCC); however, no equivalent mutations in STN1 or TEN1 have yet been identified in the same cohorts of patients." (PMID 24835988, 2014).
infertile (1 paper, 2017). "In fact, a concomitant increase of EMX2 and Ten-1 was recently reported in the endometrium of infertile patients with Müllerian duct anomalies, and the authors suggested a role for EMX2-mediated upregulation of Ten1 in this pathology." (PMID 28472127, 2017).
papillary thyroid carcinoma (1 paper, 2017). "Further, two recent articles reported a prognostic impact of Ten-1 overexpression in papillary thyroid carcinoma and prolactin pituitary tumors, respectively." (PMID 28472127, 2017).
thyroid carcinoma (1 paper, 2022). "In contrast, TEN1 was upregulated in LUSC, KIRC, PRAD, thyroid carcinoma (THCA), and UCEC (p < 0.05)." (PMID 35368664, 2022).
cancer (1 paper, 2022). A tumor composed of atypical neoplastic, often pleomorphic cells that invade other tissues. "The survival analyses reveal two cancer groups in which both CS score and TEN1 are significantly associated with survival." (PMID 35368664, 2022). "Cox regression revealed that CTC1, STN1, the CS score, and the CST score were associated with better survival in at least four cancer types, while TEN1 was associated with worse survival only in LGG." (PMID 35368664, 2022). "However, TEN1 was associated with better survival in nine cancer types and with worse survival in six cancer types." (PMID 35368664, 2022). "Some cancer types were found with both alterations of TEN1 amplification/CTC1 deletion (LIHC) or both of CTC1/STN1 deletions (PRAD) or all of the TEN1 amplifications and CTC1/STN1 deletions (BRCA and UCEC)." (PMID 35368664, 2022). "In contrast, the second cancer group had six cancer types exhibiting an opposed survival pattern for CS score and TEN1." (PMID 35368664, 2022). "The first cancer group contained nine cancer types showing a consistent survival pattern for CS score and TEN1." (PMID 35368664, 2022). "First, tumors have less CTC1/STN1 but more TEN1 expression than their adjacent normal tissues in a majority of cancer types." (PMID 35368664, 2022). "By setting a stringent cutoff as having a correlation with CS or TEN1 in at least 10 from the 33 cancer types, we discovered both positively (in red) and negatively (in blue) correlated compounds." (PMID 35368664, 2022). "TEN1 may help to resolve replication stress to facilitate cancer cell growth." (PMID 35368664, 2022). "Interestingly, by mining the miRNA-target interaction database and analyzing the correlation between miRNA and CST expression, we found that CTC1 and STN1, but not TEN1, could be repressed by multiple miRNAs in various cancer types." (PMID 35368664, 2022).
tumor (1 paper, 2022). "When comparing the expression of CST between tumor and paired adjacent normal samples, we found that CTC1 and STN1 were largely downregulated, whereas TEN1 was upregulated in tumors." (PMID 35368664, 2022). "Our work suggests that CTC1 and STN1, but not TEN1, are putative tumor suppressors." (PMID 35368664, 2022).
TEN1 also shares sentences with these, for which no sentence is quoted: brain tumors (1 paper); colon adenocarcinoma (1); colon cancer (1); diffuse large B-cell lymphoma (1); lymphoid neoplasm (1); male infertility (1); mesothelioma (1); ovarian carcinoma (1); pituitary tumor (1); prostate adenocarcinoma (1); uterine carcinosarcoma (1).